OPA1 (OPA1 mitochondrial dynamin like GTPase)
Diseases named in the same sentence as OPA1 in open-access papers (continued):
Sharing a sentence is not in itself a finding about the gene and the disease.
steatosis (2 papers, 2023). Increased lipid within the cytoplasm of cells. "Consistently, H&E and Oil Red O staining revealed greatly decreased steatosis in OPA1-KO liver in HFD whereas marked steatosis in floxed liver was observed." (PMID 37872238, 2023). "Mfn1, Mfn2, and Opa1 mRNA expression in steatosis LO2 cells was also significantly lower, while the mRNA expression levels of Fis1 and Drp1 were much higher than those in the control (p < 0.01) and the taurine groups (p < 0.01)." (PMID 37373507, 2023). "As our data show that OPA1 KO induces mitohormesis to protect liver from drug toxicity and steatosis, the liver mitohormesis can be considered another mechanism contributing to the liver resiliency." (PMID 37872238, 2023).
Strabismus (2 papers, 2020 to 2022). A misalignment of the eyes so that the visual axes deviate from bifoveal fixation. "The rare variants in OPA1 and COL4A1 were inherited from the father who had strabismus as a child, suffered from a traumatic macular haemorrhage in the left eye as an adolescent and went through cataract surgery in adulthood." (PMID 32040484, 2020).
type 1 diabetes (2 papers, 2023 to 2025). "Interestingly, it has been demonstrated that a significant decrease in Opa1 expression in coronary endothelial cells in a type 1 diabetes mouse model possibly contributes to excessive mitochondrial fission and mitochondrial ROS production." (PMID 40616272, 2025).
viral infection (2 papers, 2022 to 2025). "One month after stereotactic injection, we verified the upregulation of OPA1 expression in the CA1 following viral infection using RT-PCR and Western blot." (PMID 40354372, 2025). "To evaluate the roles of OPA1 in LUAD, we knocked down OPA1 through virus infection (shRNAs) in the NCI-A549 cell line." (PMID 36573240, 2022).
ZIKV infection (2 papers, 2020 to 2025). "In correlation with the sequencing results, qRT-PCR data also show increased expression levels of MFN1 and OPA1 following ZIKV infection." (PMID 32902370, 2020). "Silencing of Bmal1 combined with ZIKV infection resulted in alternations of the expression of several mitochondrial proteins, including the pDRP1s616/DRP1 ratio, MFF, and OPA1 in brain endothelial cells." (PMID 40313764, 2025).
Akinesia (1 paper, 2013). Inability to initiate changes in activity or movement and to perform ordinary volitional movements rapidly and easily. "As Opa1 morphants had movement defects such as akinesia (inability to initiate movement) and Bradykinesia (slow movement), this decrease in basal respiration is most likely due to decreased movement and ATP demand." (PMID 23516612, 2013).
Anxiety (1 paper, 2023). Intense feelings of nervousness, tension, or panic often arise in response to interpersonal stresses. "Here, we demonstrate that eight- to nine-month-old OPA1-deficient animals display normal locomotor activity, motivation, and anxiety level." (PMID 37863658, 2023).
Aortic valve disease (1 paper, 2023). "Protein tyrosine phosphatase 1B inhibition improves mitochondrial dynamics by regulating OPA1 homeostasis to alleviate calcified Aortic valve disease." (PMID 37603376, 2023).
Arrhythmia (1 paper, 2016). Any cardiac rhythm other than the normal sinus rhythm. "Altogether, these results indicate that in Opa1+/- cardiomyocytes, mitochondrial Ca2+ uptake is impaired, whereas the late repolarization phase of APs is markedly increased with an enhanced arrhythmia triggering." (PMID 27723783, 2016). "Simultaneous whole-cell patch-clamp recordings of mitochondrial Ca2+ movements and ventricular action potential (AP) showed impairment of dynamic mitochondrial Ca2+ uptake and a marked increase in the AP late repolarization phase in conjunction with greater occurrence of arrhythmia in Opa1+/- mice." (PMID 27723783, 2016). "Furthermore, 50% of Opa1+/- cardiomyocytes were triggered soon after depolarization (6/12 cells), whereas no such arrhythmia was observed in WT cardiomyocytes." (PMID 27723783, 2016).
Ascites (1 paper, 2021). Accumulation of fluid in the peritoneal cavity (between the layers of the peritoneum that lines the abdomen). "In an ascites susceptible selected line of broilers, OPA1 expression has been shown to decrease under ascites conditions in the lungs, thigh, and breast compared to an ascites resistant selected line." (PMID 33634182, 2021).
autosomal dominant optic atrophy plus syndrome (1 paper, 2022). "One of these also had an OPA1 mutation and was reclassified as autosomal dominant optic atrophy-plus syndrome." (PMID 34006618, 2022).
cerebellar degeneration (1 paper, 2010). Degeneration of the cerebellum. "The fundamental importance of mitochondrial remodelling in mammalian pathophysiology has been underlined by in utero lethality and cerebellar degeneration in mice with homozygous mutations in Dnm1l itself, as well as Mfn1, Mfn2, or Opa1." (PMID 20585624, 2010).
Charcot-Marie-Tooth type 2 (1 paper, 2017). "Interestingly, mutations in MFN2 are associated with Charcot-Marie-Tooth type 2 (CMT2) while mutations in OPA1 are the major cause of dominant optic atrophy." (PMID 28376086, 2017).
chronic kidney disease (1 paper, 2025). Impairment of the renal function secondary to chronic kidney damage persisting for three or more months. "Dramatically, restoration of YME1L1 expression significantly alleviates cisplatin‐induced AKI and subsequent chronic kidney disease (CKD) through attenuating mitochondrial dysfunction via maintaining optic atrophy 1 (OPA1)‐mediated mitochondrial energy metabolism homeostasis." (PMID 39680752, 2025).
colitis (1 paper, 2022). Inflammation of the colon. "MFN1, MFN2, OPA1, and p-DRP1 levels increased in a model of DSS-induced colitis." (PMID 35035669, 2022).
colorectal adenocarcinoma (1 paper, 2023). The most common type of colorectal carcinoma. "Notably, the type of alterations in the OPA1 gene in colorectal adenocarcinoma cases were all mutations (~2% frequency)." (PMID 37980164, 2023).
disc degeneration (1 paper, 2024). "For the first time, we report the importance of OPA1 in maintaining the morphology of several organelles in the NP cells and show that conditional deletion of OPA1 (Opa1AcanCreERT2) causes disc degeneration, osteoarthritis and osteopenia in aged mice." (PMID 38464287, 2024). "Noteworthy, Opa1AcanCreERT2 mice with Opa1 deletion in disc and cartilage showed age-dependent disc degeneration, osteoarthritis, and vertebral osteopenia." (PMID 38464287, 2024).
Endometrial Cyst (1 paper, 2023). It is caused by endometriosis, and formed when a tiny patch of endometrial tissue (the mucous membrane that makes up the inner layer of the uterine wall) bleeds, sloughs off, becomes transplanted, and grows and enlarges inside the ovaries. "Increased oxidative stress and ROS accumulation have been found in serum, peritoneal fluid, and ectopic endometrial cysts in patients with endometriosis, which can reduce the expression of MFN1, MFN2, and OPA1, compatible with our result." (PMID 37393390, 2023).
endometriosis (1 paper, 2023). The growth of functional endometrial tissue in anatomic sites outside the uterine body. "We detected elevated DRP1, OPA1, MFN2, and LCLAT1 in eutopic ESCs in patients with endometriosis than in controlled group." (PMID 37393390, 2023). "Here, we demonstrated a decline in mRNA and protein expression levels of DRP1, OPA1, MFN1, and MFN2 in ectopic ESCs and tissue and a decrease in mitochondrial number in endometriosis." (PMID 37393390, 2023).
endothelial dysfunction (1 paper, 2022). In vascular diseases, endothelial dysfunction is a systemic pathological state of the endothelium (the inner lining of blood vessels) and can be broadly defined as an imbalance between vasodilating and vasoconstricting substances produced by (or acting on) the endothelium. "Defects in mitochondrial biogenesis and the disturbance of OPA1 and DRP1 turnover will result in cell apoptosis and contribute to the endothelial dysfunction and the pathogenesis of cardiovascular diseases." (PMID 36232649, 2022).
epilepsy (1 paper, 2015). A brain disorder characterized by episodes of abnormally increased neuronal discharge resulting in transient episodes of sensory or motor neurological dysfunction, or psychic dysfunction. "In many genotypes, such as m.14709T>C, OPA1, and PEO1, no patients with epilepsy were found." (PMID 26381753, 2015).
fibrosis (1 paper, 2021). the formation of excess fibrous connective tissue in an organ or tissue in a reparative or reactive process. "The deacetylated, active form of OPA1 corrects cardiac fibrosis and malfunction, OPA1 deacetylation via SIRT3 being the only known post-translational change that activates OPA1." (PMID 34829803, 2021).
fungal infections (1 paper, 2018). "Therefore, pharmacological activation of OPA1 in neutrophils might be a new option for fighting bacterial and fungal infections." (PMID 30054480, 2018).
glomerular disease (1 paper, 2026). "While our study establishes the role of OMA1 in mitigating glomerular disease in PHB2-deficiency, we did not directly assess OPA1 cleavage in podocytes." (PMID 41509918, 2026).
glomerulosclerosis (1 paper, 2023). A hardening of the kidney glomerulus caused by scarring of the blood vessels. "In a mouse model, the increase of OPA-1, a master regulator of mitochondrial cristae morphology, reduces mitochondrial damage from various causes, including mitochondrial DNA depletion-induced glomerulosclerosis and sorafenib-induced (an anticancer agent) hepatocyte apoptosis." (PMID 36851021, 2023).
Glucose intolerance (1 paper, 2021). Glucose intolerance (GI) can be defined as dysglycemia that comprises both prediabetes and diabetes. "BAT-derived FGF21 is also dispensable for the improvements in glucose homeostasis and insulin sensitivity in OPA1 BAT KO mice, as HFD-induced glucose intolerance was attenuated in DKO mice, and fasting glucose levels were reduced." (PMID 33944779, 2021).
hereditary ataxia (1 paper, 2018). An instance of an atactic disorder that is caused by an inherited genomic modification in an individual. "The clinical features of these patients may also overlap at various stages of the disease with other more common forms of mitochondrial disease, such as LHON, OPA1, and POLG-related disease, and may mimic other forms of hereditary ataxia." (PMID 29506874, 2018).
Hypoglycemia (1 paper, 2022). A decreased concentration of glucose in the blood. "Upregulation of PGC-1α and OPA1 is observed in hypoglycemia 28,30, consistent with previous data 18 in terms of enhancing β-oxidation and promoting the TCA cycle for ATP production." (PMID 35469048, 2022).
hypogonadism (1 paper, 2010). A disorder characterized by decreased function of the gonads. "Another OPA1 mutation (p.Tyr582Cys) is responsible for progressive hearing loss that necessitated cochlear implantation, macrocytic anemia, and hypogonadism." (PMID 20069065, 2010).
hypothyroidism (1 paper, 2024). Abnormally low levels of thyroid hormone. "As OPA1 and OMA1 are critical for the maintenance of mitochondrial integrity and function, their decline suggests an impaired mitochondrial fusion process in hypothyroidism, likely leading to mitochondrial dysfunction and impaired cellular energy production." (PMID 39301315, 2024). "On the other hand, the livers of hypothyroid rats treated with either 3,5-T2 or T3 exhibit increased mitochondrial fusion, as evidenced by increased OPA1 and OMA1 levels, possibly counteracting the deleterious effects of hypothyroidism on mitochondrial dynamics." (PMID 39301315, 2024).
kidney injury (1 paper, 2026). Trauma to the kidney. "In a mouse model of ischemic kidney injury, mitochondrial fragmentation due to OPA1 proteolysis by OMA1 has been implicated as a contributing factor to renal tubular injury and could be rescued by OMA1 ablation." (PMID 41509918, 2026).
liver fibrosis (1 paper, 2022). "Last but not least, Mfn1 and Opa1 were downregulated in schistosomiasis-induced liver fibrosis, and lipoic acid treatment upregulated Mfn1 and Opa1 and alleviated fibrosis." (PMID 35933403, 2022).
lung diseases (1 paper, 2025). "Furthermore, the age‐related mtDNA damage in lung diseases tends to upregulate mitochondrial fusion‐related proteins such as MFN1 and optic atrophy‐1 protein (OPA1) to compensate mitochondrial deficiencies." (PMID 39668579, 2025).
lymphoma (1 paper, 2025). A malignant (clonal) proliferation of B- lymphocytes or T- lymphocytes which involves the lymph nodes, bone marrow and/or extranodal sites. "OMA1 activation causes excessive proteolytic cleavage of OPA1 and increased integrated stress response (ISR)-induced apoptosis in lymphoma cells." (PMID 41146909, 2025). "More specifically, BTM pyrazolo-thiazoles (BTM-3528 and BTM-3566) selectively kill lymphoma cells by allosterically turning on OMA1, which then cleaves its two key substrates, OPA1 and DELE1, to couple mitochondrial dynamics to the ISR and intrinsic apoptosis." (PMID 41146909, 2025). "In lymphoma cell lines like BJAB and HCT-116, BTM compounds cause OMA1-dependent loss of long OPA1, inducing fission, without the immediate mitochondrial depolarization or acute respiration impairment." (PMID 41146909, 2025).
lymphopenia (1 paper, 2021). Reduction in the number of lymphocytes. "Our data show that Opa1 deficiency starting from early thymocyte development results in lymphopenia and metabolic defects in mature T cells." (PMID 33649469, 2021). "Accordingly, OPA1 is required during thymocyte β-selection and Opa1 deficiency alters TCR signaling in thymocytes, resulting in lymphopenia and impaired metabolism of mature T cells." (PMID 33649469, 2021).
memory impairment (1 paper, 2023). "Overall, our data demonstrate that OPA1 deficiency leads to memory impairment in hippocampal-dependent tasks (spatial navigation in the Barnes maze, object location and pattern separation) while sparing memory in hippocampal-independent tasks (object recognition, cued Barnes maze)." (PMID 37863658, 2023).
mtDNA depletion syndromes (1 paper, 2019). "Importantly, the degree of mtDNA depletion we see in MSTO1 patient fibroblasts (30–70% of the normal content) is consistent with the levels of mtDNA depletion reported in fibroblasts from OPA1 or MFN2 patients as well as in mtDNA depletion syndromes." (PMID 31463572, 2019).
muscle disorders (1 paper, 2014). "Taken together, our data provide evidence indicating that mitochondrial dysfunction-associated OPA1 cleavage may contribute to muscle degeneration, and olive oil compounds could be effective nutrients for preventing the development of muscle disorders." (PMID 25393477, 2014).
myeloid leukemia (1 paper, 2018). A clonal proliferation of myeloid cells and their precursors in the bone marrow, peripheral blood, and spleen. "Reduction of OPA1 mRNA expression, but not any of the other dynamin-like GTPases, was associated with a complete inability to release DNA with either differentiated human myeloid leukemia cells or mouse Hoxb8 neutrophils." (PMID 30054480, 2018).
Myocardial fibrosis (1 paper, 2018). "Our results demonstrated that TLR4 activation mainly led to OPA1 dysfunction, which accompanied by increased cardiomyocyte apoptosis, myocardial fibrosis, ventricular dilatation, and declined heart function." (PMID 30046376, 2018).
non-alcoholic fatty liver disease (1 paper, 2023). "On the other hand, OPA1 depletion in the mouse liver was shown to rather decrease the non-alcoholic fatty liver disease (NAFLD) and nonalcoholic steatohepatitis (NASH) pathologies." (PMID 37872238, 2023).
oncocytic tumors (1 paper, 2025). "Notably, MFN2, OPA1, DRP1, and FIS1 have been found to be overexpressed in oncocytic tumors, independent of mitochondrial content." (PMID 40485730, 2025).
Optic disc pallor (1 paper, 2022). A pale yellow discoloration of the optic disc (the area of the optic nerve head in the retina). "In this study, 11 probands from 11 unrelated Chinese ADOA families presented varying vision defects and optic disc pallor, and were all identified as carrying heterozygous OPA1 variants." (PMID 35883160, 2022).
Pancytopenia (1 paper, 2023). An abnormal reduction in numbers of all blood cell types (red blood cells, white blood cells, and platelets). "In our study, we analyzed the role of OPA1 in the development of pancytopenia." (PMID 37980164, 2023).
polyneuropathy (1 paper, 2023). A disease or disorder affecting more than one nerve. "Of the patients with nuclear genes associated with mitochondrial diseases (POLG1 and OPA1), only one patient with OPA1 affected by polyneuropathy showed mild cochlear hearing loss." (PMID 37763097, 2023).
prostate carcinoma (1 paper, 2015). A carcinoma that arises from epithelial cells of the prostate gland. "Interestingly, in prostate cancer cells, researchers found that EGFR induced mitochondrial fusion through upregulation of OPA1 and involve in de novo synthesis of the fatty acid, palmitate." (PMID 26497368, 2015).
schizophrenia (1 paper, 2013). A major psychotic disorder characterized by abnormalities in the perception or expression of reality. "Shotgun mass spectrometry study on dorsolateral prefrontal cortex from patients with schizophrenia has shown differential expression of OPA1." (PMID 23521751, 2013).
scrapie (1 paper, 2018). A fatal disease of the nervous system in sheep and goats, characterized by pruritus, debility, and locomotor incoordination. "Furthermore, there is a significant decrease in Drp1 in scrapie-infected mice in the terminal stages of disease (139A, ME7 and S15), levels of OPA1 showed a tendency to decrease, and abnormalities of Drp1 and OPA1 were primarily localized to neurons." (PMID 30455640, 2018).
Skeletal myopathy (1 paper, 2022). "Coactivation of these pathways does not necessarily occur in skeletal myopathy, because muscle depleted of the mitochondrial fission protein Drp1, or OPA1, shows ISR but not mTORC1 activation." (PMID 35531957, 2022).
soft tissue sarcoma (1 paper, 2023). A malignant neoplasm arising from muscle tissue, adipose tissue, blood vessels, fibrous tissue, or other supportive tissues excluding the bones. "Patients with complex genomic soft tissue sarcoma showed variations in the level of OMA1 and OPA1 transcripts." (PMID 37024121, 2023).
tauopathy (1 paper, 2025). Neurodegenerative disorders involving deposition of abnormal tau protein isoforms (tau proteins) in neurons and glial cells in the brain. "In this study, we observed an upregulation of the mitochondrial fission protein DRP1 in the SH‐SY5Y tauopathy model, while the levels of fusion proteins MFN1, MFN2, and OPA1 remained unchanged." (PMID 40344412, 2025).
thyroid tumor (1 paper, 2015). A benign or malignant neoplasm affecting the thyroid gland. "The expression of mitochondrial fusion (Opa1, Mfn1 and Mfn2) and fission (Drp1 and Fis1) proteins were evaluated by immunohistochemistry (IHC) in a series of 88 human thyroid tumors." (PMID 25822260, 2015).
uterine cancer (1 paper, 2022). Primary or metastatic malignant neoplasm involving the uterine corpus and/or the cervix. "Our analysis indicated that among the fusion genes, OPA1 was significantly overexpressed in AML, breast, colon, esophageal, lung, ovary, pancreatic, rectum, renal, stomach, testis, and uterus cancer tissues." (PMID 35279198, 2022).
α-synucleinopathy (1 paper, 2021). "Given the alterations in Drp1 levels in the TgA53TG2-3 models, we examined whether the expression of MFN1, OPA1, and Fis1 was altered as a function of α-synucleinopathy." (PMID 33924585, 2021).